HP (haptoglobin)
Diseases named in the same sentence as HP in open-access papers (continued):
Sharing a sentence is not in itself a finding about the gene and the disease.
Sepsis (continued). "Lastly, the understanding gained from our studies showing longer stored blood having increased hemolysis with release of CFH and iron led to a promising new therapeutic candidate for sepsis treatment—haptoglobin." (PMID 38362479, 2020). "When designing future clinical trials of haptoglobin use in human sepsis, it will be important to understand and account for these factors promoting CFH clearance." (PMID 38362479, 2020). "Previous studies have also suggested the administration of haptoglobin as a therapeutic strategy against lethal sepsis and liver injury." (PMID 31568522, 2019). "Haptoglobin, a protein that binds free hemoglobin is protective against sepsis pathogenesis and has been shown to decrease in the acute phase after sepsis." (PMID 30804939, 2019). "Altogether, these results suggest that in critically ill sepsis patients, the production of haptoglobin cannot be induced as normal, enabling sepsis to progress in severity." (PMID 31568522, 2019). "The current study suggests a role for haptoglobin in adults with sepsis beyond its past descriptions as an acute-phase reactant." (PMID 24225252, 2013). "We sought to determine the association of plasma levels of endogenous free hemoglobin and haptoglobin and hemopexin with in-hospital mortality in adults with sepsis." (PMID 24225252, 2013). "In animal models of sepsis, supplementation with haptoglobin or hemopexin decreases biomarkers of inflammation, reduces the incidence of acute lung injury, improves organ function, and decreases mortality." (PMID 24225252, 2013). "Prospective studies, including randomized trials, are needed to better elucidate the potential protective effects of endogenous and exogenous haptoglobin against the deleterious effects of cell-free hemoglobin in patients with sepsis." (PMID 24225252, 2013). "Low haptoglobin levels are reported in various clinical conditions, including tumor metastasis, severe sepsis, hemolytic anemia and chronic liver disease 27,28." (PMID 20556197, 2009). "Given the protective role of haptoglobin in neutralizing cell-free hemoglobin toxicity, future research should explore its therapeutic potential in mitigating hemolysis-related complications in sepsis." (PMID 40429487, 2025). "Given its influence on cytokine networks, a targeted therapeutic could be designed to either enhance or inhibit specific haptoglobin interactions, offering new treatment strategies for conditions such as sepsis, chronic inflammatory diseases, and even cancer." (PMID 40606553, 2025). "Haptoglobin is an acute-phase reactant and may be elevated in inflammation, infection, or tissue injury, which are common in sepsis." (PMID 40429487, 2025). "Our findings reveal markers of the microvascular response to sepsis which include increased levels of HP, C3, Chil3/CHI3L1, and MMP8 both at the transcriptomic level in mouse and human kidney microvasculature and at the protein level in circulating plasma of SA-AKI patients." (PMID 40892345, 2025). "The present study reveals that in comparison with sepsis patients who had serum haptoglobin levels below 100 mg/dL upon ICU admission, those with levels exceeding 200 mg/dL exhibited a 34.5 % decrease in the risk of AKI (OR = 0.655, 95 % CI 0.439‒0.976, p = 0.038)." (PMID 40743649, 2025). "However, the effects of meldonium pretreatment appear to be less pronounced when followed by FIP sepsis, as haptoglobin levels were similar in both septic groups." (PMID 40371344, 2025). "Elevated plasma haptoglobin levels have been observed in sepsis." (PMID 40429487, 2025). "Finally, ARG1 and HP were identified as valuable diagnostic markers and nomogram maps were developed to improve early identification of SAP-associated sepsis." (PMID 39364223, 2024). "Previous reports have shown that HP levels increase in both pediatric and adult with sepsis." (PMID 39364223, 2024).
Sepsis (continued). "In addition to the higher levels of CRP and haptoglobin observed, we found a very significant increase in IL-1Ra, IL-6, and IL-8 in the blood of all animals 24 h after sepsis onset." (PMID 38087374, 2023). "Additionally, exercise seems to amplify the haptoglobin response to sepsis (♂:190%, P = 0.001 and ♀:297%, P = 0.0001) in males and female animals." (PMID 37407986, 2023). "Haptoglobin is another biomarker for hemolysis, but its level may change in several critical conditions including sepsis or red blood cell transfusion." (PMID 33402152, 2021). "Among them, plasma CD14, HP (acute-phase reaction proteins and involved in oxidative stress pathways), and hemopexin (an anti-inflammatory molecule and an oxidative scavenger) were increased in early sepsis." (PMID 34745104, 2021). "For patients with leukocyte levels below this threshold, HP expression can be assessed on the tertiary level for the risk of sepsis (specificity = 0.9657; negative predictive value = 0.9174; positive predictive value = 0.6428; AUC = 0.8219)." (PMID 26607226, 2015). "As the role of cell-free hemoglobin in the pathophysiology of sepsis is better elucidated, haptoglobin as a potential therapeutic will likely be attractive since both animal and human studies of diseases associated with increased cell-free hemoglobin have suggested a protective effect." (PMID 24225252, 2013). "For sepsis prognosis, five proteins were significantly up-regulated: selenium binding protein-1, heparan sulfate proteoglycan-2, alpha-1-B glycoprotein, haptoglobin, and lipocalin; two proteins were significantly down-regulated: lysosome-associated membrane proteins-1 and dipeptidyl peptidase-4." (PMID 23372690, 2013). "Increased haptoglobin may play a protective role in sepsis patients who have elevated levels of circulating cell-free hemoglobin beyond its previous description as an acute phase reactant." (PMID 24225252, 2013). "•Haptoglobin and hemopexin may only provide protection in patients with sepsis in the setting of elevated cell-free hemoglobin levels." (PMID 24225252, 2013). "Thirdly, the absence of free hemoglobin data in this database precludes us from assessing whether sepsis patients may experience haptoglobin depletion due to elevated levels of free hemoglobin, and whether sufficient levels of haptoglobin could counteract the renal injury induced by free hemoglobin." (PMID 40743649, 2025). "Therefore, elevated expression of HP in monocytes among patients may indicate an increased likelihood of sepsis in clinical settings." (PMID 39710434, 2024). "We suspected that PFKFB2 might be the target gene of HP in the glycolysis of sepsis." (PMID 38227599, 2024). "ARG1 and HP may affect SAP and sepsis by regulating inflammation and immune responses, shedding light on potential future diagnostic and therapeutic approaches for SAP-associated sepsis." (PMID 39364223, 2024). "Additionally, HP is involved in the immune response to sepsis." (PMID 38227599, 2024). "Hence, this would seem to suggest that the dip in HP protein observed, could be a useful new biomarker for sepsis progression." (PMID 31568522, 2019). "Additionally, the potential protective effect of haptoglobin against mortality in sepsis may only occur in the setting of detectable plasma cell-free hemoglobin." (PMID 24225252, 2013). "Haptoglobin and hemopexin are endogenous scavengers of cell-free hemoglobin and cell-free heme, respectively, and have been shown in animals and humans to attenuate oxidant injury and to reduce inflammation, acute lung injury, and mortality in animals with sepsis." (PMID 24225252, 2013). "Plasma levels of cell-free hemoglobin are associated with mortality in patients with sepsis; however descriptions of independent associations with free hemoglobin and free heme scavengers, haptoglobin and hemopexin, are lacking beyond their description as acute phase reactants." (PMID 24225252, 2013).
Sepsis (continued). "Our findings align with these studies, as half of the patients in our cohort exhibited elevated haptoglobin levels upon ICU admission, likely reflecting the systemic inflammatory response characteristic of sepsis." (PMID 40429487, 2025). "Given the overwhelming inflammation in response to infection in sepsis, the protein content of the inflammatory markers HMGB1 and haptoglobin was evaluated." (PMID 40371344, 2025). "In order to assess the linear correlation between serum haptoglobin and AKI in sepsis patients, the authors utilized a smooth curve fitting approach." (PMID 40743649, 2025). "In rats with FIP sepsis, elevated PAB and AOPP levels, along with reduced haptoglobin expression and CD73 activity, indicate significant protein damage in this region." (PMID 40371344, 2025). "Moreover, while haptoglobin is being explored as a therapeutic target in conditions such as haemolytic anaemias, sepsis, and cardiovascular diseases, there is still insufficient understanding of how specific modulation of haptoglobin activity could be leveraged to improve clinical outcomes." (PMID 40606553, 2025). "Using RT-qPCR, we confirmed the upregulation of HP, C3, Chil3/CHI3L1, and MMP8 in renal microvascular compartments in both CLP-sepsis mice and human post-mortem kidney biopsies from patients with SA-AKI." (PMID 40892345, 2025). "Therefore, NRBCs may actively suppress excessive inflammation that is dangerous to the self in systemic inflammatory conditions such as sepsis and systemic juvenile idiopathic arthritis by increasing haptoglobin levels and suppressing inflammatory function of monocytes." (PMID 40017804, 2025). "Our diagnostic nomogram incorporates critical insights into the NLR signaling pathway, particularly through the hub genes ARG1 and HP, which bridge SAP and sepsis." (PMID 39364223, 2024). "For instance, in sepsis samples, high expression of HP and low expression of IRF6 were consistently observed, whereas in normal samples, the pattern was opposite with low HP expression and high IRF6 expression across all datasets." (PMID 39710434, 2024). "ARG1 and HP, identified as crucial hub genes between SAP and sepsis, play a vital role in the immunological response." (PMID 39364223, 2024). "Three machine learning results revealed that two overlapping genes (ARG1, HP) were identified as shared hub genes for SAP and sepsis." (PMID 39364223, 2024). "In the cell experiments, it was found increased expression of HP and PFKFB3 in sepsis, and there existed a positive relation between them." (PMID 38227599, 2024). "Our research indicates that both ARG1 and HP were upregulated in SAP and sepsis and showed good predictive properties with an AUC ≥0.800 in both test and validation sets." (PMID 39364223, 2024). "Our study highlights the potential of key genes, such as HP and PFKFB3, to uncover novel regulatory pathways and identify key molecular targets for improving sepsis diagnosis, treatment and prognosis." (PMID 38227599, 2024). "We found that ARG1 and HP are the most important hub genes between SAP and sepsis, and the NLR signaling pathway is a common regulatory pathway for these two diseases." (PMID 39364223, 2024). "Using specific ELISA parameters, we analyzed the levels of porcine CRP, haptoglobin, IL-4, IL-10, PGE2, TGF-ß and porcine alpha-1 acid glycoprotein, as we considered these to be fundamental sepsis biomarkers according to existing clinical research." (PMID 38087374, 2023). "However, recent animal studies of haptoglobin supplementation for treatment of increased cell-free hemoglobin in sepsis have created new interest in these biomarkers as potential endogenous protectants against morbidity and as well as potential therapeutics in humans with sepsis." (PMID 24225252, 2013). "Upregulation of HP, C3, Chil3/CHI3L1, and MMP8 in renal microvascular compartments of both mice and humans may reflect endothelial activation in sepsis, as supported by prior transcriptomic and proteomic studies." (PMID 40892345, 2025).
Sepsis (continued). "•Highlights haptoglobin's potential for AKI prevention and intervention in sepsis." (PMID 40743649, 2025). "The results showed the mRNA and protein levels of HP and PFKFB2 were both up-regulated in sepsis." (PMID 38227599, 2024). "Thus, we suspect that there is certain relation among HP, PFKFB2, glycolysis and neutrophils in sepsis." (PMID 38227599, 2024). "Expression of HP, QSOX1 (HR = 1.129, p > 0.05), and PGLYRP1 (HR = 1.062, p > 0.05) did not have a statistically significant predictive effect on the survival of patients with sepsis." (PMID 35145983, 2022). "To determine if the beneficial effect of Hp therapy was limited only in the setting of blood transfusion, as a control group we also studied haptoglobin infusion in canines with sepsis alone who did not receive transfusion of blood." (PMID 38362479, 2020). "Haptoglobin, LBP, and the serpins in particular responded with a clear linear increase in plasma levels over the first 24 h after SE infection, suggesting their high relevance as early markers of sepsis and bacterial infection." (PMID 31803186, 2019). "We attempted to control for possible confounders with logistic regression models, however it is possible that there are unmeasured confounder, and haptoglobin is only a marker of severity of illness rather than a potential protective mediator in sepsis." (PMID 24225252, 2013). "Therefore, HP, C3, Chil3/CHI3L1, and MMP8 have established roles in immune modulation, inflammation, and the oxidative stress response, and our study demonstrates their upregulation as part of the endothelial activation signature in sepsis." (PMID 40892345, 2025). "Compared with classical blood biomarkers of systemic inflammation (e.g., CRP), the proteins detected in this study, including haptoglobin, vWF, MBL1, MRC1, sCD14, and LBP, showed a very early response to infection, indicating their potential in serving as new early markers of infection or sepsis." (PMID 31803186, 2019). "However, the relationship between haptoglobin and AKI in sepsis patients remains unclear." (PMID 40743649, 2025). "Lung specific alterations in some of these proteins (e.g. SP-A and haptoglobin) could serve as targets for novel therapies in future research; however, rhAPC treatment was associated with only modest changes in the LPS response, consistent with its lack of clinical benefit in ALI or modest sepsis." (PMID 19432985, 2009).
malaria (45 papers, 2007 to 2026). Malaria is a serious and sometimes fatal disease caused by a parasite that commonly infects a certain type of mosquito which feeds on humans. "Proteogenomics of haptoglobin in infected host blood aided understanding of the correlation between the gene and protein of polymorph in haptoglobin co-dominant alleles to understand the malaria progression." (PMID 34943459, 2021). "The interaction we describe here between Sl2 and α+thalassaemia is reminiscent of the epistatic interactions that have been observed between α+thalassaemia and other malaria-protective polymorphisms including sickle cell trait (HbAS) and haptoglobin." (PMID 29690995, 2018). "The sensitivity and specificity of haptoglobin (>1.1 mg/mL) in discriminating respiratory distress caused by pneumonia from that caused by malaria were 92.8% and 99.2%, respectively." (PMID 24696240, 2014). "The diagnostic performance of Lpc-2 and haptoglobin in discriminating respiratory distress caused by pneumonia or malaria was evaluated in an independent population of 293 Kenyan children." (PMID 24696240, 2014). "The HP CNV/Hb-related associations are possibly derived from malaria-driven positive selection, mediated through the selective advantage of the Hp2 allele mitigating the deleterious effects of haemolysis and subsequent oxidation damage." (PMID 22433445, 2012). "Other proteins that were unique or up-regulated in malaria cases like calmodulin, fibrinogen gamma chain and haptoglobin are associated with inflammation, endothelial vascular damage and haemolysis." (PMID 22640863, 2012). "The derived Hp2 allele of the HP gene has apparently been subject to malaria-driven positive selection." (PMID 22433445, 2012). "Polymorphisms of the haptoglobin (HP) gene and deletions in α-globin gene (α-thalassaemia) are common in malaria-endemic Africa." (PMID 18554871, 2008). "Polymorphisms of the haptoglobin (HP) gene and deletions in the α-globin gene (α-thalassaemia) are very common in malaria-endemic Africa and both the HP2-2 polymorphism and α-thalassaemia have been associated with protection against malaria." (PMID 18554871, 2008). "Haplotype prevalence was 10.3% and 14.2% for D and E haplotypes in analyses of haptoglobin concentration compared to 13% for both haplotypes in analysis of malaria susceptibility." (PMID 17426810, 2007). "Furthermore, the combination of Lpc-2 with haptoglobin discriminates between pneumonia and malaria-associated respiratory distress." (PMID 24696240, 2014). "We reasoned that a marker of hemolysis such as haptoglobin could discriminate respiratory distress caused by pneumonia from that caused by severe malaria because haptoglobin levels increase with pneumonia severity and decrease with malaria severity owing to erythrocyte destruction." (PMID 24696240, 2014). "This suggests that in adult mice the accumulation of labile heme in serum during malaria is controlled by HP and HPX." (PMID 38307624, 2024). "An overlapping set of genes, HP, ICAM1, IFNG, TLR2, and TLR4 were found to contain SNPs statistically significantly associated with malaria in both maternal and child analyses." (PMID 37287037, 2023). "In contrast, poor performances, especially for malaria severity prognosis, were reported for other biomarkers, including IL-6, haptoglobin, apolipoprotein E, serum amyloid A, Ang-1, ICAM-1, and platelet count." (PMID 36036460, 2022). "In a study of 390 Gambian children, haptoglobin and lipocalin-2 were able to discriminate with high accuracy between acute respiratory infection and severe malaria with respiratory distress (area under receiver operating characteristics (AUROC) = 0.99)." (PMID 32314692, 2020). "In this study, the relationship between haptoglobin genotypes and incidence of uncomplicated malaria in a cohort of children living in a malaria-endemic area of Uganda was determined." (PMID 33243242, 2020).